NF2 (NF2, moesin-ezrin-radixin like (MERLIN) tumor suppressor)
Diseases named in the same sentence as NF2 in open-access papers (continued):
Sharing a sentence is not in itself a finding about the gene and the disease.
meningioma (continued). "The CNV status associated significantly with levels of DNA methylation, such that CNV-high NF2 mutant meningiomas displayed a hypermethylated phenotype, particularly affecting the PRC2 targets in embryonic stem cells." (PMID 28195122, 2017). "Conversely, alterations in NF2 or chromosome 22 occurred significantly more frequently in high-grade (80%) than low-grade meningiomas (43%, p < 1 × 10−16)." (PMID 28713588, 2017). "First, genome-wide DNA methylation patterns clearly separated the NF2 mutant meningiomas from relatively less methylated non-NF2 tumours, with atypical non-NF2 meningiomas clustering distinctly from benign non-NF2 ones." (PMID 28195122, 2017). "Here, we present an in-depth genomic study of benign and atypical meningiomas, both from a single NF2 patient." (PMID 28193203, 2017). "For example, secretory meningiomas were driven exclusively by TRAF7/KLF4 co-mutations, while fibrous meningiomas were primarily associated with NF2 loss." (PMID 28195122, 2017). "Other than NF2, the most frequently mutated genes were CDC27 and LRP1B, mutated in 10 (9%) and 9 (8%) samples, respectively, of the total set of 115 meningiomas." (PMID 28713588, 2017). "Sporadic meningiomas with disrupted NF2 tend to display greater genomic instability (including several cases of chromothripsis) and higher grades than non-NF2 meningiomas." (PMID 28193203, 2017). "We characterized 31 RIMs with exome/NF2 intronic sequencing, RNA sequencing and methylation profiling, and found NF2 gene rearrangements in 12/31 of RIMs, an observation previously unreported in sporadic meningioma (SM)." (PMID 28775249, 2017). "In a previous study comprised predominately of sporadic meningiomas, an NF2 rearrangement was previously observed in a single case, interestingly from a patient with a prior history of cranial radiation." (PMID 28775249, 2017). "We calculated the significance of association of the driver mutations (NF2, SMARCB1, TRAF7/PI3K, TRAF7/KLF4, POLR2A, Hedgehog) with atypical meningiomas." (PMID 28195122, 2017). "OGN appears to downregulate NF2, the canonical tumor suppressor altered in approximately half of meningiomas." (PMID 28923059, 2017). "We next identified tumour suppressor genes located within these genomic regions frequently deleted in atypical NF2 meningiomas." (PMID 28195122, 2017). "To discover additional NF2 intronic rearrangements in an expanded cohort of meningiomas we designed a targeted sequencing panel to capture both exons and introns of NF2 within 31 RIMs and 30 sporadic meningiomas." (PMID 28775249, 2017). "The NF2 gene is located on the long arm of chromosome 22, which is a region commonly involved in meningioma tumorigenesis." (PMID 27007654, 2016). "It has been shown that different WHO meningioma grades display similar frequency of NF2 inactivation which suggests that NF2 changes are early event in the etiology of this tumour." (PMID 27429002, 2016). "Next-generation sequencing has characterized recurrent somatic mutations in NF2, TRAF7, KLF4, AKT1, SMO, and PIK3CA, which are collectively present in ~80% of sporadic meningiomas." (PMID 27458586, 2016). "The increased penetrance for males for meningiomas in childhood is also found both in sporadic meningiomas and NF2 with the reverse being true in adulthood." (PMID 26803492, 2016). "The development of meningiomas in NF2-knockout mice corroborates its role as an early oncogenic driver in meningioma tumorigenesis." (PMID 27458586, 2016). "Alternative splicing and frequent codeletion of CHEK2 with NF2 in meningiomas harbouring chromosome 22q deletions impaired DNA repair in their study and increased chromosomal instability, thus promoting meningioma progression." (PMID 27429002, 2016). "A meningioma in childhood can be the first presenting symptom of neurofibromatosis type 2 (OMIM 101000), caused by mutations in the NF2 gene." (PMID 26803492, 2016).
meningioma (continued). "To further understand the role of merlin/NF2 in mTORC1 activation, we undertook an unbiased kinome screen in NF2-null meningioma cells." (PMID 26219339, 2015). "An arachnoid cell (AC07) and two NF2+/+ meningioma cell lines MN328 (benign) and MN525 (malignant) were assessed for sensitivity to Pak inhibitors." (PMID 25596744, 2015). "To assess the relationship between PDGF-B expression and NF2 status, we performed PDGFR-B immunohistochemistry on a Tissue Array of 54 meningiomas of all grades with known NF2 status." (PMID 26418719, 2015). "Our previous work demonstrated aberrant activation of mTORC1 signaling that led to ongoing clinical trials with rapamycin analogs for NF2 and sporadic meningioma patients." (PMID 26219339, 2015). "These assays showed that all the Pak inhibitors repressed the invasiveness of benign and malignant NF2-null meningioma cells by 70% and ~40%, respectively." (PMID 25596744, 2015). "Loss of Nf2 and Cdkn2ab have synergistic effects with PDGF-B overexpression promoting meningioma malignant transformation." (PMID 26418719, 2015). "In contrast to NF2, the promoter methylation of tissue inhibitor of metalloproteinase 3 (TIMP3), located quite close to the NF2 gene, is inactivated in meningiomas." (PMID 26101774, 2015). "PDGFR-B immunopositivity was found in 54% of meningiomas and statistically more frequent in NF2- tumors compared to NF2+ tumors (23/36 vs. 6/18, χ2, p = 0, 03)." (PMID 26418719, 2015). "Nf2 mutant mice (Nf2+/−) do not develop schwannomas or meningiomas, and selective Cre-mediated excision of Nf2 in arachnoidal cells results in development of benign (grade I) meningioma in mice." (PMID 26219339, 2015). "Subsequent studies carried out in mouse models reported that rapamycin suppressed the growth of meningiomas in a xenograft model and delayed the growth of NF2-related Schwann cell tumorigenesis." (PMID 26219339, 2015). "Our earlier work in human meningioma cells demonstrating the activation of mTORC1 led to clinical trials with rapamycin analogs for NF2 and sporadic meningioma patients." (PMID 26219339, 2015). "Patients with NF2 present with bilateral schwannomas and other tumors, frequently meningiomas, which originate from arachnoid cells, and account for 20% of all primary intracranial tumors." (PMID 25333347, 2014). "The importance of the NF2 gene to nervous system tumor formation is further underscored by the finding that NF2 locus alterations predominate in sporadic (non-NF2-related) schwannomas, meningiomas, and ependymomas." (PMID 25243094, 2014). "Substantial evidence from previous studies indicated that the main genetic event in meningioma initiation is inactivation of the NF2 gene, accounting for 30 to 70% of sporadic meningiomas." (PMID 25247996, 2014). "Whereas the hallmark of this disorder is bilateral vestibular (VIIIth cranial nerve) schwannoma development, individuals with NF2 also harbor other cranial and peripheral nerve schwannomas, meningiomas, and spinal ependymomas." (PMID 25243094, 2014). "A recent genomic study in paired progressive meningiomas also demonstrated that NF2 gene inactivation is an early and frequent event in progressing meningioma samples and is associated with higher chromosome instability during progression." (PMID 25247996, 2014). "Due to the common genetic origin of these tumors (NF2 inactivation), previous studies have attempted to identify targets with which to inhibit both schwannoma and meningioma progression." (PMID 25333347, 2014). "Other genetic non-NF2 aberrations of oncogenes have been observed in skull base and higher-grade meningiomas." (PMID 25485306, 2014). "Our results for NF2-related meningiomas are comparable to case series of sporadic meningiomas treated with bevacizumab." (PMID 23555840, 2013). "Both in vitro and in vivo treatment showed a selective anti-proliferative effect on schwannoma and meningioma cells warranting further clinical evaluation for NF2 related tumors." (PMID 24259290, 2013).
meningioma (continued). "Because multiple meningiomas are common in NF2 patients, we analyzed our data on a per-tumor basis and on a per-patient basis." (PMID 23555840, 2013). "In this study, we report on the frequency of NF2 mutations in a group of 20 sporadic WHO grade I/benign meningiomas and its association with the distinct genetic and histopathological subtypes of meningiomas." (PMID 24171707, 2013). "To determine the clinical activity of bevacizumab against NF2-related meningiomas, we measured changes in volume of meningiomas in NF2 patients who received bevacizumab for treatment of progressive vestibular schwannomas." (PMID 23555840, 2013). "Meningioma was the first solid tumor shown to contain a recurrent genetic alteration e.g. monosomy 22/del(22q), NF2 being the most relevant gene involved." (PMID 24171707, 2013). "In our previous investigation on meningiomas, two LOHs of the NF2 gene were found with the D22S929 marker." (PMID 22911524, 2012). "Seven of the 72 patients are known to have died, three as a direct result of their meningioma and four patients with NF2 died as a result of multiple tumors." (PMID 22543431, 2012). "NF2 is characterized by bilateral vestibular schwannomas, spinal cord schwannomas, meningiomas and ependymomas, and juvenile cataracts." (PMID 22436304, 2012). "Neurofibromatosis type 2 (NF2) is a tumour-prone disorder characterised by the development of multiple schwannomas and meningiomas." (PMID 19545378, 2009). "Approximately 60% of sporadic meningiomas have NF2 gene involvement and promoter methylation again plays a significant role." (PMID 19545378, 2009). "At very young ages (< 18 years) individuals presenting with an apparently isolated meningioma or vestibular schwannoma are have a 20% and 10% likelihood respectively of developing NF2." (PMID 19545378, 2009). "Chromosome 22 deletion is a frequent mechanism for somatic inactivation of the NF2 gene, thought to account for ~60% of meningiomas." (PMID 19589153, 2009). "Follow‐up of these early meningiomas with a non‐invasive imaging technique provides an additional readout in preclinical studies for chemoprevention of NF2‐related tumors." (PMID 17924978, 2008). "The neurofibromatosis type 2 (NF2) tumor suppressor is the only gene known to be frequently involved in early development of meningiomas." (PMID 17222329, 2007). "Despite almost 40 years of cytogenetic and molecular genetic research, the NF2 tumor suppressor is still the only specific gene which has been shown to be frequently involved early in the development of meningiomas." (PMID 17222329, 2007). "Transcriptional silencing of the NF2 tumor suppressor by CpG methylation in meningiomas was recently tested by two research groups, but the results were conflicting." (PMID 17222329, 2007). "In this study, we analysed a protein product of the neurofibromatosis type 1 (NF1) gene, neurofibromin, in human established leptomeningeal cells LTAg2B, in 17 sporadic meningiomas and in a meningioma from a patient affected by NF2." (PMID 9310240, 1997). "The reduced expression and GTPase stimulatory activity of neurofibromin was found in about 23% of meningiomas and in the single NF2-related meningioma analysed." (PMID 9310240, 1997). "While germline NF2 mutations (NF2-SWN) often lead to meningiomas and vestibular schwannomas, somatic NF2 mutations are common in sporadic meningiomas and should not suggest NF2-SWN." (PMID 42088105, 2026). "Ultimately, the insights gained from NF2-mutant meningiomas may be generalizable to other tumors (e.g., mesothelioma) with synthetic lethal architectures." (PMID 41487565, 2025). "The large number of meningiomas in NF2 also complicates treatment decisions." (PMID 40820211, 2025). "In this case, genetic testing was not performed, as the patient did not have clinical features of NF2 or other genetic syndromes associated with meningiomas, and genetic testing resources were limited." (PMID 40283561, 2025).
meningioma (continued). "Therefore, a study comprising matched meningioma and VS from the same NF2-SWN patients would be valuable in providing a more in-depth and high dimensional spatial interrogation of these two tumour types in the target patient group." (PMID 41437121, 2025). "While tumor location is not a diagnostic criterion, high-grade meningiomas are more common in convexity and non-skull base areas, which often harbor chromosome 22q deletions and/or NF2 mutations." (PMID 40936721, 2025). "Some of these agents have shown significant activity against NF2-driven schwannoma and meningioma." (PMID 41160189, 2025). "Our results revealed benign NF2-mutant and MC ben-1 meningiomas exhibited the higher proportions of M2-like TAMs, especially brain-resident microglia and M2-like microglia, whereas aggressive MC mal tumours showed an increased presence of monocyte-derived macrophages and M2-like macrophages." (PMID 40420192, 2025). "While NF2 gene inactivation has long been recognized as a key driver of meningioma tumorigenesis, more recent studies have identified non-NF2 alterations, particularly those involving the TRAKLS genes (TRAF7, AKT1, KLF4, SMO), as well as other genetic changes not otherwise classified." (PMID 40951339, 2025). "Activation of the μ‐calpain system, which mediates proteolytic cleavage and degeneration of Merlin, has been reported to result in loss of Merlin expression in some cases of schwannomas and meningiomas without NF2 alteration." (PMID 40815185, 2025). "Neurofibromatosis type 2 (NF2) gene mutation and/or 22q deletion are frequent in meningiomas, but are not yet included in the WHO classification." (PMID 40447281, 2025). "NF2-SWN is an autosomal dominantly inherited condition predisposing affected individuals to the development of schwannomas, meningiomas and ependymomas as well as specific ophthalmologic manifestations (posterior subcapsular or cortical cataracts, epiretinal membranes)." (PMID 41160189, 2025). "About 50% of sporadic meningiomas harbor NF2 gene mutations, suggesting that these tumors have no or reduced merlin expression." (PMID 40447281, 2025). "Drug repurposing may offer an expedited route to the clinical translation of approved drugs effective for treating both meningioma and vestibular schwannoma to benefit NF2-related schwannomatosis patients." (PMID 41437121, 2025). "NF-2 alterations, alongside high Ki-67 proliferative indices and supratentorial location, have been associated with poorer prognosis in terms of PFS for patients presenting with grade I meningiomas." (PMID 40918813, 2025). "On the other hand, schwannomas, meningiomas, and ependymomas are the key manifestations of NF-2." (PMID 40416267, 2025). "In meningiomas without NF2 alterations, mutations in TRAF7, KLF4, AKT1, SMO, PIK3CA and POLR2A are recurrent alterations." (PMID 40815185, 2025). "The extent to which the NF2-FAK model can be generalized beyond meningiomas remains uncertain." (PMID 41487565, 2025). "The management of NF2-associated meningiomas, both with and without signs of increased intracranial pressure (ICP), is complex due to the presence of numerous other tumors and pre-existing neurological impairments." (PMID 40820211, 2025). "Meningiomas and ependymomas are also important manifestations of NF2." (PMID 40852360, 2025). "TRAF7 mutations are exclusive to meningiomas without NF2 alterations and are enriched in secretory meningioma." (PMID 41372821, 2025). "PI3K/Akt/mTOR pathway targeting was justified by its putative role in the tumorigenesis of meningiomas that may stem from NF2 inactivation." (PMID 40149634, 2025). "Typically, problems related to intracranial pressure arise predominantly in adulthood for NF2 patients and may be related to the increasing growth dynamics of the meningiomas." (PMID 40820211, 2025).
meningioma (continued). "NF2 status is increasingly important in meningioma diagnostics and we questioned whether merlin immunohistochemistry could be used as an accessible and affordable surrogate marker for prediction of NF2 mutations." (PMID 40447281, 2025). "Some NF2-inactivated meningiomas may also be marked by accumulation of CNAs, and the acquisition of co-occurrent CNAs involving chromosomes 1p, 1q, 9p, or 18q may be particularly prognostic in this context." (PMID 40603285, 2025). "However, since we used grade 1 NF2-mutant meningioma cells, further investigation across other classifications is necessary to fully understand the role of M2-like macrophages in tumour progression." (PMID 40420192, 2025). "However, the presence of multiple tumors, including bilateral vestibular schwannomas, trigeminal schwannomas, and meningiomas, strongly supports NF2." (PMID 40821302, 2025). "Phospho-Merlin expression was observed in non-NF2 meningiomas." (PMID 40420192, 2025). "Prospective clinical studies of FAK targeted therapy in NF2-mutant meningiomas and gliomas." (PMID 41487565, 2025). "Neurofibromatosis type 2 (NF2) is a rare genetic disorder affecting the nervous system, primarily characterized by benign tumor formation, including bilateral vestibular schwannomas, meningiomas, and ependymomas." (PMID 40821302, 2025). "Neurofibromatosis type 2 (Nf2) gene inactivation is common in sporadic and Nf2‐related meningioma." (PMID 39996452, 2025). "Additionally, it has been shown that aggressive NF2 mutant meningiomas downregulate oncogenic YAP1 signaling." (PMID 40936721, 2025). "Such alternative explanations cannot be fully ruled out, as biological and design-related differences between GBM and NF2-mutant meningioma may also have contributed to the divergent clinical outcomes." (PMID 41487565, 2025). "For instance, NF2-status may influence the infiltration of various inflammatory cells in the meningioma tissue." (PMID 40359417, 2025). "On the contrary, there were five cases of NF2 meningioma with retained IHC pattern of Merlin." (PMID 40815185, 2025). "In addition to Nf2, other mutations have also been identified, such as TRAF7, KLF4, and P16, which are related to the malignant progression of meningiomas." (PMID 39996452, 2025). "However, with the discovery and analysis of more YAP fusion meningioma cases, certain subtypes such as YAP1-FAM118B fusion, these meningiomas exhibit distinct biological characteristics from NF2 mutant meningioma." (PMID 39894505, 2025). "Therefore, molecular validation of meningioma findings (e.g., NF2, AKT1, TRAF7) and an increase in both sample size and tumour subtype diversity are important for enhancing the reliability and generalizability of future studies." (PMID 41009755, 2025). "Therefore, NF2 should be considered in the differential diagnosis of meningiomas in pediatric patients." (PMID 40821302, 2025). "Positive PDL1 expression was observed in NF2‐meningiomas, downregulation of PD‐L1 could inhibit tumor cell proliferation, promote apoptosis, and suppress the inhibitory effect of tumor cells on T‐cell activation and cytotoxicity." (PMID 38828669, 2024). "Notably, genetic alterations were not only reported to be frequently found in meningiomas (e.g., NF2 and TRAF7) but also specifically found in each case." (PMID 38238738, 2024). "In addition, we showed that the meningioma/schwannoma-derived NF2 LOF mutations not only compromised its tumor suppressive function in the Hippo pathway, but also gained an oncogenic role for NF2 by activating the VANGL-JNK pathway." (PMID 39572544, 2024). "The Kalamarides lab has previously developed several meningioma GEMMs relying on the Adenovirus Cre (AdCre)-mediated deletion of the Nf2 gene in PGDS (Prostaglandin D synthase)-expressing arachnoid cap cells in mice either in a wild-type or Cdkn2a null background." (PMID 38571886, 2024).